IL18 (interleukin 18)
Diseases named in the same sentence as IL18 in open-access papers (continued):
Sharing a sentence is not in itself a finding about the gene and the disease.
colitis (continued). "K pneumoniae can induce colitis through activation of caspase-11 and release of interleukin 18 in gut epithelial cells." (PMID 36436756, 2023). "Through the assembly of an inflammasome, NLRP6 was shown to prevent dextran sodium sulfate (DSS)-induced colitis by regulating IL-18 levels in colonic epithelial cells." (PMID 36613400, 2023). "On the other hand, plasma levels IL-18 are elevated in ulcerative colitis patients; and murine models revealed a paradoxical role for IL-18 in colitis, depending on disease stage." (PMID 38163085, 2023). "Using in vivo model, they found that colitis severity was controlled at the level of IL-18 signaling and the role of goblet cell dysfunction in the IBD pathogenesis." (PMID 37383609, 2023). "Transplantation of bone marrow cells from IL18 KO into CD45.1+ WT or WT into CD45.2+IL18 KO mice did not produce significantly different effects on KLPJ-mediated colitis, indicating that IL18 in gut epithelial cells plays a main role in KLPJ-mediated colitis." (PMID 36436756, 2023). "NLRP6 expression in intestinal epithelial cells protects against colorectal cancer and colitis via a mechanism dependent on caspase-1 mediated IL-18 production." (PMID 36761775, 2023). "To illustrate that gut epithelial cell–derived IL18 plays a main role in KLPJ-mediated colitis, we performed bone marrow transplant experiments." (PMID 36436756, 2023). "The authors also revealed that protection was mediated via IL-18 secretion, with an injection of exogenous recombinant IL-18 partially alleviating the inflammatory symptoms of DSS-induced colitis." (PMID 37240022, 2023). "While IL-18 has been purported to have protective roles in colitis, subsequent work suggests that IL-18 mediates inflammation and epithelial barrier dysfunction." (PMID 35832789, 2022). "In colitis, IL-18 contributes to dysfunction by depleting goblet cells and weakening the mucosal barrier." (PMID 35334805, 2022). "Mice deficient in the autophagic protein ATG16L1 exhibited a specific increase of Interleukin (IL)-1β and IL-18 in macrophages and severe colitis, which was ameliorated by anti-IL-1β and IL-18 antibody administration." (PMID 35780157, 2022). "Network of cytokines including IL-1β, TNF-α, IL-6, IL-10, IFN-γ, and IL-18, have been reported to regulate mucosal inflammation in colitis, and IL-6, TNF-α are viewed as therapeutic targets in IBD." (PMID 35330829, 2022). "Double knock out of IL-1β and IL-18 cytokines increased transgenic mice protection from TNBS colitis induction compared to deletion of either cytokine." (PMID 36032110, 2022). "For example, ENS neuron-derived IL-6 regulates RORγt+ Tregs differentiation and epithelial-derived IL-18 regulates Tregs function in a colitis model." (PMID 35844606, 2022). "Administration of exogenous recombinant IL-18 attenuates colitis in mice with inflammasome defects, further supporting the protective role of IL-18 in colitis." (PMID 35677444, 2022). "Reports are suggesting that IL-1β and IL-18 induced by the NLRP3 inflammasome confer protection against colitis and colitis-associated tumorigenesis." (PMID 36389791, 2022). "In a colitis model, IL-18 is critical in driving the pathological breakdown of intestinal barrier integrity; deletion of IL-18 conferred protection from colitis and mucosal damage in mice." (PMID 35935959, 2022). "In colitis mouse models, inflammasome activation led to an increase in both IL-18 production and mucosal barrier integrity, resulting in a decreased hepatic bacterial load." (PMID 36313762, 2022). "Accordingly, in murine models of inflammation including DSS colitis, recombinant IL-18 BP suppressed disease severity." (PMID 36032110, 2022). "We used a colitis model in Rag1−/− mice under an IL-18 blockade condition, which led to both decreased ILCP mobilization and exacerbated inflammation in the colon." (PMID 36417511, 2022).
colitis (continued). "IECs resistant to colitis produces antimicrobial peptides (AMPs) when they are stimulated by IL-18 processed by the NLRP6 inflammasome." (PMID 35677444, 2022). "CP-25 regulated macrophage polarization from a M1 to a M2 phenotype to attenuate DSS-induced colitis and inhibited IL-1β and IL-18 production in mice." (PMID 36457713, 2022). "NLRP1 and downstream IL-18 reduced the amount of beneficial butyrate-producing Clostridiales in the gut, aggravating experimentally-induced colitis." (PMID 36313762, 2022). "Nevertheless, a recent study showed that IL-18 is directly responsible for promoting goblet cell dysfunction during colitis, leading to mucosal barrier breakdown by inhibiting goblet cell maturation." (PMID 35677444, 2022). "Some papers reported that IL-18 had a protective role in colitis, and some other reports showed that IL-18 had a pro-colitogenic role in experimental colitis." (PMID 34721422, 2021). "Our results show that Cyld deficiency resulted in severe colitis, which was associated with an increased level of NLRP6 inflammasome activity and IL-18 in the colonic mucosa." (PMID 33910012, 2021). "On the one hand, studies with knock-out mice suggested a critical role of IL18 in protection from intestinal inflammation and colitis while on the other hand IL18 was shown to promote goblet cell dysfunction and breakdown of the mucosal barrier." (PMID 34879060, 2021). "Here, we indicated that dysregulated microbiota-driven GSDMD activation promoted colitis development by inducing IL-18 release." (PMID 34721422, 2021). "GSDMD is activated by the dysregulated microbiota and in turn mediates microbiota-driven colitis by promoting IL-18 release." (PMID 34721422, 2021). "Herein, our study found that dysregulated microbiota activated GSDMD, which in turn mediated DSS-induced colitis development by promoting IL-18 release." (PMID 34721422, 2021). "Further studies demonstrated that the colitis in mice carrying activated Nlrp1 was dependent on IL-18." (PMID 33808793, 2021). "In contrast to the results reported by Tye and colleagues, the Williams laboratory observed that both IL‐1β and IL‐18 are responsible for the attenuation of colitis." (PMID 34705319, 2021). "These investigators observed that NLRP3 activation leads to the secretion of IL‐18, which protects the host from colitis." (PMID 34705319, 2021). "Release of IL-18 was detected from both intestinal epithelial cells and lamina propria lymphocytes during colitis." (PMID 34721422, 2021). "In this study, clear increases in IL-1β and IL-18 were observed in the colonic mucosae of mice with DSS-induced colitis." (PMID 34462641, 2021). "Studies have shown that Astragalus polysaccharide reduces NLRP3 inflammasome activation and IL-1β and IL-18 levels in DSS-induced colitis." (PMID 34462641, 2021). "In a mice colitis model, IL-18 signaling induced the breakdown of barrier integrity and reduced goblet cell maturation in the intestine." (PMID 34943057, 2021). "Epithelial cells from these mice produced reduced levels of IL-18, and exogenous IL-18 reversed the increased colitis." (PMID 33808793, 2021). "It has been reported that DSS-induced colitis can promote the release of proinflammatory mediators.Therefore, the serum levels of IL-18 and IL-1β were detected by ELISA, which were prominently increased in the UC group compared with the control group." (PMID 34394827, 2021). "In our study, we found that the protein level of IL-18 was reduced in the colon culture medium of Gsdmd-/- mice during DSS-induced colitis." (PMID 34721422, 2021). "IL-18 has been shown to promote Treg reparative function via amphiregulin, and IL-18 signaling from epithelial cells to Tregs is required for protection against colitis in the RAG transfer model." (PMID 34433692, 2021). "Collectively, these data suggest that GSDMD promotes IL-18 release during colitis; and that the activation of GSDMD is required for its release." (PMID 34721422, 2021).
colitis (continued). "Administration of taurine showed reduced spermine and histamine levels and induced IL‐18 production, improved microbiota composition and had a protective effect against colitis via NLRP6 inflammasome." (PMID 33682108, 2021). "In terms of CRC, it has been reported that increased susceptibility of dextran sulfate sodium (DSS)-induced colitis and colitis-associated tumorigenesis in NLRP3−/− and IL18−/− mice, respectively." (PMID 33821998, 2021). "IL-18/IL-18R signaling in intestinal epithelial cells was also shown to drive DSS colitis in mice, whereas IL-18BP protected mice from colitis, suggesting a colitogenic function of IL-18." (PMID 33562334, 2021). "Dietary fiber and SCFA acted on G-protein coupled receptor GPR43 of colonic epithelial cells to activate the NLRP3 inflammasome and further ameliorate DSS-induced colitis through IL-18-mediated gut homeostasis." (PMID 33227973, 2020). "They found that IL-18 treatment at an earlier stage of colitis changed colon length, reduced inflammatory infiltration, and increased Muc2 expression." (PMID 32466125, 2020). "Another cytokine, interleukin-18 was increased in the BUT and PROP treatments, however, while IL-18 has been previously reported to promote barrier function and intestinal homeostasis, it can also exacerbate damage induced by colitis." (PMID 32240190, 2020). "In these studies, it was observed that the greatest susceptibility to the development of colitis in ASC-/-, NLRP6-/-, NLRP1-/-, NLRP3-/-, AIM2-/- or caspase-1-/- mice was related to a decrease in IL-18 levels." (PMID 32545788, 2020). "For instance, in the gut, IL18 signaling promotes Treg function preventing colitis; while in the lung, IL18 signaling induces production of amphiregulin in Tregs, a growth factor promoting tissue repair and homeostasis." (PMID 32687059, 2020). "Polymorphism in the NLRP3 gene is linked to colitis severity and progression in patients, and gain-of-function mutations in the NLRP3 gene that increase the production and secretion of IL-1β and IL-18." (PMID 32545788, 2020). "In a mouse model of colitis, neutralization of IL-18 was shown to reduce IFN-γ production and improve intestinal inflammation." (PMID 33143375, 2020). "On the other hand, the second and more recently postulated theory, demonstrated that Cas-1−/− mice had an even more aggravated colitis, probably due to the insufficiency of IL-18, which is an early trigger of tissue repair." (PMID 32659925, 2020). "It was shown in mouse models that gut epithelial IL-18 favored colitis and inflammation-induced cancer, whereas it was protective in established cancer." (PMID 33255437, 2020). "Treatment with caspase-1 inhibitors alleviated DSS-induced colitis and showed that IL-18-mediated cytokine production was an important factor in DSS-induced colitis." (PMID 33143375, 2020). "NLRP6-/- mice exhibit reduced IL-18 levels in intestinal epithelial cells and, interestingly, like Ogg1-/- mice were highly susceptible to DSS-induced colitis." (PMID 31935236, 2020). "Here, we found that DSS significantly increased the serum and colonic levels of IL-1β and IL-18 in colitis mice." (PMID 33312339, 2020). "First theory suggests that mice treated with Pralnacasan, a CAS-1 inhibitor, or with IL-1R antagonist experienced a significantly less severe colitis, due to a lower expression of IL-1β and IL-18." (PMID 32659925, 2020). "In a mouse model of colitis, SCFAs decreased the severity of colitis by activating NLRP3 as well as IL-18 secretion through GPR43 and GPR109A." (PMID 31091682, 2019). "To induce relative long-lasting antibodies, we developed IL-18 peptide-based virus-like particle vaccines and evaluated their therapeutic effects in a murine colitis model." (PMID 31428451, 2019). "In the present study, for the first time, we developed IL-18 peptide-based virus-like particle vaccines and evaluated the effects of these vaccines in acute and chronic murine colitis." (PMID 31428451, 2019).
colitis (continued). "The mechanisms of regeneration, then, can also be studied in the DSS colitis model and have led to the discovery of the involvement of GM-CSF, Wnt pathway, and IL-18 or IL-33." (PMID 31015842, 2019). "Using murine IBD models, deletion of il-18 or its receptor il-18r1 has been shown to be protective against inducible colitis, by controlling goblet cell function and maintaining intestinal barrier homeostasis." (PMID 31276585, 2019). "Evidence from the DSS colitis model has led to interests in the development of anti-IL-18 therapy, which will be evaluated in clinical trials (NCT03681067)." (PMID 31015842, 2019). "Intriguingly, treatment with exogenous recombinant IL-18 restored epithelial permeability, colitis, and the tumor burden." (PMID 30717382, 2019). "This corroborates our findings in experimental models of colitis in which colonic expression of IL-18 increased in response to QBECO treatment—resulting in marked improvements in gastrointestinal histopathology and barrier function." (PMID 31380382, 2019). "Considerable evidence supports the idea that NLRP3 inflammasome plays a pro-inflammatory role in colitis pathology, and blockage of IL-1β or IL-18 has been reported to reduce colitis." (PMID 30823406, 2019). "For example, the administration of IL-18BP substantially reduced the pathology in mouse models of experimental arthritis, colitis, endotoxin shock, and type 1 diabetes, disease models in which IL-18 is important for the pathology." (PMID 30717382, 2019). "In this regard, differential actions of IL-18 have been also described during the acute and chronic stages of colitis." (PMID 30619282, 2018). "In vivo, inhibition of Cbl with an analgesic drug, hydrocotarnine, increases inflammasome-mediated IL-18 secretion in the colon, and protects mice from dextran sulphate sodium-induced colitis." (PMID 30382081, 2018). "In the DSS-induced animal model of colitis, treatment with hydrocotarnine increased IL-18 secretion and protected mice from the disease." (PMID 30382081, 2018). "Consistently, hydrocotarnine can enhance IL-18 secretion in response to NLRP3 inflammasome activation in vitro and enhance IL-18 secretion in vivo in the colon of mice with DSS-induced colitis." (PMID 30382081, 2018). "Since IL-18 production downstream of the NLRP3 inflammasome is critically involved in protection against colitis and colorectal tumorigenesis, we further determine IL-18 production in colon." (PMID 30382081, 2018). "Although genetic deletion of IL-1R did not rule out a contribution from IL-1β downstream of Nlrp1 in DSS-colitis, it did implicate IL-18 in this process." (PMID 30214011, 2018). "Intra-rectal administration of CST reduced the severity of experimental colitis, IL-18 colonic levels, maintained TJ proteins and enhanced the phosphorylation of STAT3." (PMID 30241336, 2018). "Here the authors show that, in mouse experimental colitis models, Nlrp1 inflammasome sensor activates IL-18 to reduce beneficial colonic Clostridiales species, thereby decreasing microbial butyrate and its protective effects on colitis." (PMID 30214011, 2018). "IL-18 bp is a negative regulator of IL-18, a gene critical in driving intestinal barrier breakdown leading to colitis." (PMID 30227886, 2018). "The observation that Nlrp3R258W × Il18−/− mice lose resistance to DSS-induced colitis is probably due to the more predominant and frontier role of IL-18 in the epithelium than NLRP3 in the lamina propria." (PMID 29196621, 2017). "In parallel using our mouse model of colitis, we demonstrated that exogenous CHR treatment reduced the weight loss and colonic IL-18 release." (PMID 28951733, 2017). "Studies have reported that a deletion of IL-18 protected against experimental colitis and minimized the mucosal damage through maintenance of the epithelium equilibrium, demonstrating the importance of IL-18." (PMID 28951733, 2017).
colitis (continued). "Our observation that IL-18 is higher in the Nlrp3R258W mice colon after DSS colitis is likely due to there being less damage to the epithelium in these mice, which allows more efficient generation of IL-18 from the epithelium under challenge." (PMID 29196621, 2017). "Gpr109a-null mice also show decreased IL-18 production and increased population of Prevotellaceae, both alterations leading to potentiation of experimentally induced colitis." (PMID 28796169, 2017). "In detail, IL-18 can enhance colitis-induced proliferation at the early stage but suppress the proliferation at late stage." (PMID 28360909, 2017). "While numerous studies indicate the protective role of inflammasomes and IL-18 in DSS-induced colitis, recent studies demonstrate inflammasome-mediated IL-1β drives chronic inflammation in IL-10 KO mice and in human patients with IL-10R deficiency." (PMID 28955343, 2017). "ATG16L1−/− mice show high IL-1βand IL-18 levels in sera in response to LPS stimulation or during colitis." (PMID 27821816, 2016). "Hyperactive IL-18 signalling induced colitis by breakdown of the mucosal barrier through induced goblet cell loss." (PMID 27578924, 2016). "Although we found that both IL-1β and IL-18 played a protective role in OXA-induced colitis, the roles of these cytokines on colonic inflammation are inconclusive and controversial." (PMID 27966619, 2016). "To determine the involvement of IL-18 in driving IEC proliferation and inhibiting cell death in the Casp11−/− colitis model, we also stained colon sections from the IL-18 rescue experiment for PCNA, BrdU, and TUNEL." (PMID 25548224, 2015). "Increased IL-18 and Ido1 levels have been shown to play a protective role in mice during experimental colitis." (PMID 26456940, 2015). "In support of our findings, IL-18−/− and IL-18R−/− mice also have increased susceptibility to acute DSS colitis, highlighting the key role of this cytokine in intestinal regeneration and repair." (PMID 25548224, 2015). "NLRP6 deficient mice develop sever colitis in response to DSS when compared to wild type mice, manifested with reduced IL-18 expression by IECs and increased pathology." (PMID 24886810, 2014). "(iv) DSS-induced colitis was associated with an increase in circulating IL6, IL18, and NPY, an increased expression of COX-2 mRNA in the hypothalamus, and a decreased expression of BDNF, NPY, and MR mRNA in the hippocampus." (PMID 25414650, 2014). "In the colitis model small differences were seen with regard to splenic and hepatic inflammation, although this was IL-18 independent." (PMID 25115174, 2014). "Recent findings have put forward a novel concept for the dual function of IL-18 in intestinal inflammation and colitis-driven CRC." (PMID 25071785, 2014). "In fact, both IL-18 and IL-18R deficient mice are more susceptible to acute DSS-induced colitis than wild-type control mice." (PMID 25071778, 2014). "Initial studies show that pharmacological inhibition of caspase-1 with Pralnacasan or neutralization of IL-18 confers resistance to experimental colitis." (PMID 24886810, 2014). "Reduced expression of IL-18 was observed in NLRP6 deficient mice, as well as increased susceptibility to chemically induced colitis." (PMID 25071778, 2014). "In fact, IL-18 and IL-18R KO mice are known to be highly susceptible to both DSS-induced colitis and colorectal tumorigenesis." (PMID 23847622, 2013). "In support of the role of IL-18 in DSS colitis, inhibition of endogenous merprin β to reduce the generation of active IL-18 was protective in DSS colitis." (PMID 24115947, 2013). "In support of this concept is the observation that IL-18 and IL-18R KO mice are more susceptible to acute DSS colitis than their WT littermates." (PMID 23847622, 2013). "Blocking IL-18 with the IL-18 binding protein (IL-18BP) also reduces colitis induced by antigen sensitization." (PMID 24115947, 2013).